BRAF (B-Raf proto-oncogene, serine/threonine kinase)
Diseases named in the same sentence as BRAF in open-access papers (continued):
Sharing a sentence is not in itself a finding about the gene and the disease.
cancer (continued). "The most common BRAF gene mutation found in human cancers is V600E, and exists in up to 22% of CCA in one report." (PMID 27102149, 2016). "First, we investigated the drug response of cells with a genomic alteration at 52 of the most frequently mutated cancer genes except BRAF." (PMID 26916442, 2016). "RNF43 was mutated in 47/54(87%) BRAF mutant/MSI and 8/33(24%) BRAF mutant/microsatellite stable cancers compared to only 3/79(4%) BRAF wildtype cancers (p<0.0001)." (PMID 27661107, 2016). "Detection of BRAF V600E mutation gene bears relationship to survival and proliferation of cancer cells." (PMID 26884744, 2016). "It has been shown that cancer cells respond to specific drugs when they harbor mutations in driver genes such as BRAF and NRAS." (PMID 27356755, 2016). "On a positive note, the diagnostic value of c.1799T>A for BRAF diagnostics is widened to many other cancers besides SKCM that homogeneously show single p.V600E substitutions like THCA, COAD, GBM, KIRP, READ, and LGG." (PMID 25600636, 2015). "The oncogenic BRAF(V600E) mutation is a common mutation in many cancers and precancerous lesions making it an important diagnostic marker and treatment target." (PMID 26091525, 2015). "Members of the MAPK signalling pathway, such as NRAS, KRAS and BRAF are among the most frequently mutated proto-oncogenes in cancer." (PMID 26090869, 2015). "More recently, new guidelines for the use of cetuximab and panitumumab treatment in CRC patients supported the analysis of the mutational status of both KRAS and NRAS genes and BRAF in wild-type RAS cancers." (PMID 26508446, 2015). "This review article summarizes the current knowledge on BRAF mutations in human and canine cancers and discusses the potential applications of this abnormality in veterinary oncology." (PMID 29061943, 2015). "A practical consequence of these findings is that since IgR39 cells are heterozygous for the BRAF V600 mutation, a drug acting on such a factor should affect both CSCs and cancer cells." (PMID 26494317, 2015). "In total, 7 PRDM5 mutations were reported from 6 cancer samples (2.0% mutation rate) that were all BRAF wild type." (PMID 25613750, 2015). "In our study, we show that patients with VE1 positive immunohistochemistry show the typical characteristics associated with BRAF mutated cancers." (PMID 26496026, 2015). "This homogeneity within primary tumors and their matched metastatic lesions also underlines previous works suggesting that BRAF mutation is a driver and an early event in tumorigenesis for cancers deriving through the so-called serrated pathway." (PMID 26496026, 2015). "This review article summarizes the current knowledge of BRAF mutations in human and canine cancers and discusses potential applications of the dysregulation of BRAF/MAPK pathway in veterinary oncology." (PMID 29061943, 2015). "Supervised hierarchical analysis using ANOVA further revealed differential expression of several proteins implicated in cancer, including BRAF, STAT5A, and the Wnt pathway-related protein DVL3." (PMID 25999352, 2015). "In this study, methylated PRDM5 associated with presence of nuclear beta-catenin in the BRAF mutant/MSI cancers." (PMID 25613750, 2015). "RAF and its isoforms, especially the serine/threonine kinase BRAF, are commonly activated by somatic point mutations in human cancers." (PMID 26431495, 2015). "Since the V600E accounts for the majority of BRAF mutations in cancer, we used its specific dbSNP Id number (rs113488022) to query CCLE genomic data." (PMID 26513174, 2015). "As cancers with BRAF mutations are often addicted to this signaling pathway, targeting BRAF signaling represents a reasonable therapeutic strategy." (PMID 25821557, 2015). "These cancers derive from serrated type precursor lesions and are hallmarked by a V600E BRAF mutation, which with the onset of CIMP are early events in this ‘serrated pathway’ of tumourigenesis." (PMID 25613750, 2015).
cancer (continued). "In the context of the Pan-Cancer study we report a detailed analysis of the mutational landscape of BRAF and other drivers across cancer tissues." (PMID 25600636, 2015). "The BRAF V600E mutation accounts for 80% of BRAF mutations in human cancers and is thought to be biologically distinct from less frequent BRAF mutations because it allows growth in the absence of functional RAS genes." (PMID 25636897, 2015). "The cobas 4800 BRAF V600 Mutation Test has been developed within the strict framework of clinical trials as a companion diagnostic for targeted cancer therapy with vemurafenib, a BRAF kinase inhibitor." (PMID 25789737, 2015). "Coupled with frequent mutations of RAS genes between human and canine cancers, the evolutionarily conserved BRAF mutations underscore the importance of MAPK pathway activation as a common oncogenic molecular pathway." (PMID 29061943, 2015). "Discovery of BRAF mutations in a wide variety of human cancers opened a new era of BRAF/MAPK targeted therapy for BRAF-mutant cancers." (PMID 29061943, 2015). "We first tested the combined down-regulation of endogenous BRAF with exogenous complementation by a BRAF V600E cancer mutation using a Donor D2.4 variant (pMDS-GOI-TETon- tTS) in HEK293 cells grown in serum-containing medium." (PMID 26612112, 2015). "An open-label multi-center study investigating the efficacy and safety of vemurafenib in patients with BRAF mutation-positive cancers, including MM, is currently recruiting participants." (PMID 26137529, 2015). "Phosphorylated ERK signal was detected in all 4-cell lines used in our experiments, suggesting that the ERK pathway plays an important role in cancer development in KRAS or BRAF mutated cells." (PMID 25706985, 2015). "By calculating the relative frequency of mutations corrected for the cohort size, other BRAF-driven cancers were identified." (PMID 25600636, 2015). "Targeting the MAP-kinase pathway component BRAF, which carries activating mutations in ∼50% of melanomas, has revolutionized the treatment of this cancer." (PMID 26174485, 2015). "Recent discovery of the BRAF mutation cBRAFV595E (orthologous to the human BRAF V600E mutation) in a variety of canine cancers underscores the importance of MAPK pathway activation in carcinogenesis." (PMID 29061943, 2015). "Since UC and PC cancer cells often shed into urine, detection of the canine BRAF mutation in urine offers utility as another non-invasive molecular diagnostics for canine UC and PC." (PMID 29061943, 2015). "While little is known about the biological role of 4/5 affected genes, BRAF represents the most frequently mutated gene encoding a protein kinase in human cancers." (PMID 26261698, 2015). "Lessons already learned from molecular studies of the BRAF pathway are relevant to almost all cancer tissues, which showed somatic missense mutations." (PMID 25600636, 2015). "The frequency of PRDM5 methylation also increased from serrated precursor lesion to BRAF mutant cancers at a similar proportion which suggests that PRDM5 methylation associates with advancing disease in cancers of the serrated pathway." (PMID 25613750, 2015). "Genetic mutations in various components of the MAPK pathway have been implicated in the progression of many human cancers, including melanoma, where BRAF mutation is present in around 50% of malignant tumors." (PMID 25804893, 2015). "This mutation results in the amino acid substitution of glutamic acid for valine at codon 450 (V450E) of canine BRAF, corresponding to the most common BRAF mutation in human cancer, V600E." (PMID 26053201, 2015). "Coupled with frequent mutations of RAS genes, the presence of BRAF mutations in a wide variety of human cancers underscores the importance of MAPK pathway activation as a common oncogenic molecular pathway." (PMID 26053201, 2015).
cancer (continued). "In summary, we uncovered the impact of the RAL signal transduction on genetic program and growth control in KRAS- and BRAF-mutated colorectal cells and demonstrated prognostic potential of the pathway-responsive gene signature in cancer patients." (PMID 26033452, 2015). "Both KRAS- and BRAF- mutated tumors were more likely to be located at proximal colon than wild-type (WT) carcinomas." (PMID 25929517, 2015). "BRAF-mutated carcinomas were more likely to be found in proximal colon than wild-type BRAF tumors (60.9% vs 20.9%, P < 0.0001)." (PMID 25929517, 2015). "To examine this association, we created cancer cell variants with wild-type BRAF in the in silico model." (PMID 24884660, 2014). "This allowed us to explore new features beyond the original CRISPR/Cas9 knockout screen design, for example, to identify new drug response genes and potential combination therapies (for example, EGFR in BRAF mutated cancer cells)." (PMID 25476604, 2014). "Feminization of cancer cells was significantly associated with microsatellite-stable CRCs (p-value 0.003) and wild-type BRAF gene status (p-value 0.009)." (PMID 25268611, 2014). "The presence of BRAF T1799A oncogene is an unfavorable prognostic factor in PTC as it increases the aggressive nature of cancer through raising its invasiveness, accelerating relapses and the occurrence of metastases BRAF gene encodes BRAF protein." (PMID 24987460, 2014). "Specifically, we examined sensitivity of cancer cells in the presence of mutations and/or over-expression of BRAF, CDH1, ERBB2, CCND1 and MET." (PMID 24884660, 2014). "Survival analyses were performed in 1067 BRAF-wild-type cancers to avoid confounding by BRAF mutation." (PMID 24885062, 2014). "Global hypomethylation is well documented in CRC where it can associate with CIN and affects predominantly BRAF wild type cancers." (PMID 24651849, 2014). "Nowadays, detecting BRAF mutation is equivalent to measuring blood glucose in that it allows identifying which cancer patients would benefit from an anti-cancer agent targeting a specific kinase (e.g., targeted theranostics against mutated BRAF)." (PMID 24982846, 2014). "In animal experiments, oncogenic KRAS and activated BRAF mutations cooperate to accelerate the rapid onset of cancer." (PMID 25013473, 2014). "An IC50 dose of 20 μM was established for Nthy-ori 3–1 and 10 μM for BCPAP, indicating that our normal thyroid cells are twice as resistant to growth-inhibiting effects of PLX4032 compared to the more susceptible BRAF-mutated cancer cells." (PMID 24673746, 2014). "Both KRAS and BRAF mutations fall into the “driver mutation” classification, since it appears to be one of the first events in the malignant transformation to cancer." (PMID 25361007, 2014). "Identification of somatic-activating mutations of BRAF has been reported in various cancers, with by far the most common mutation being a 1799 T > A transversion leading to a Val600Glu (V600E) substitution." (PMID 25267307, 2014). "Most of the BRAF mutations associated with cancer are located in exons 11 and 15, coding for the kinase domain." (PMID 25032217, 2014). "BRAF mutations (V600E in 70%-80% of all BRAF mutations in all cancers) occur early in melanomagenesis and are found in a high percentage of melanocytic nevi." (PMID 24743024, 2014). "Most importantly, activating mutations in BRAF appear to predict sensitivity to BRAF inhibitors and this is perhaps the strongest correlation of drug response with a genetic change in cancer care." (PMID 25276134, 2014). "Similar results considering BRAF or RAS mutation status are found in a large data set containing drug-treatment data from 732 cancer cell lines of different origin." (PMID 24941944, 2014). "Theoretically, mutated cancer cells are highly dependent on BRAF signaling and are unable to survive treatment while cells expressing only wild-type BRAF remain unaffected." (PMID 24673746, 2014).
cancer (continued). "In many cancers mutations that activates RAS are driven by mutations in BRAF but BRAF mutations are rare in NETs." (PMID 25546138, 2014). "We have previously conducted several studies on the role of MSI, methylation of cancer related genes and mutations of known genes such as BRAF and KRAS, as well as microarray based studies of CRC tumors from different patients' populations." (PMID 24475022, 2014). "SSAs and MSI cancers were reported to exhibit similar features including predominant location in the proximal colon, high BRAF and low KRAS mutation and enhanced DNA hypermethylation." (PMID 24964857, 2014). "An inflammatory response associated with KRAS/BRAF mutations has been reported in many human cancers, including CRC." (PMID 23755178, 2014). "To our knowledge, we are the first to report the frequency and type of KRAS and BRAF mutations in Albanian patients with advanced CRC in order to introduce targeted therapy in the therapeutic modalities for management of this cancer in Albania." (PMID 25267307, 2014). "When clinicopathological features were compared between methylation(+) cancer and methylation(−) cancer, mutations of BRAF/RAS oncogenes significantly correlated to methylation(+) groups (P = 0.04, Fisher's exact test)." (PMID 24367375, 2013). "Among the 34 cancer samples in total, 26 cancer samples with preferential methylation were significantly associated with mutation of BRAF/RAS oncogene (P = 0.04, Fisher's exact test)." (PMID 24367375, 2013). "The improved understanding of the role BRAF mutations in cancer diagnosis, prognosis and treatment has increased the need for BRAF mutation testing." (PMID 24252159, 2013). "We initially identified enrichment of five cancer-associated pathways by BRAF mutation-specific promoter methylation of nine unique genes." (PMID 23324568, 2013). "BRAF-activating mutations have been identified in many cancers as a causative determinant of hyperproliferation." (PMID 23844038, 2013). "BRAF V600E mutation is associated with reduced survival (overall survival, disease-free survival, or cancer-specific survival) especially in MSS tumors." (PMID 24298448, 2013). "We find BRAF mutations to be more common in cancers from White patients, women, older patients, and in the proximal colon consistent with other reports." (PMID 24066160, 2013). "The high frequency of RAS or BRAF mutations in these cancers makes targeting this pathway an attractive strategy for new anti-cancer agent development that relies on a patient stratification to identify individuals most likely to benefit from MAPK inhibitors." (PMID 23991070, 2013). "BRAF is mutated at a high frequency in several cancers, although also amplification of the protein and aberrant splicing variants have been reported as well." (PMID 24298448, 2013). "After the first reports of BRAF mutations in colorectal malignancy, it has soon been recognized that BRAF alterations are strongly associated with right-sided sessile cancers and its serrated precursor lesions HPs and serrated adenomas." (PMID 23845441, 2013). "Approximately 90% of all BRAF mutations identified in human cancers are a T1799A transversion in exon 15, which results in a V600E amino acid substitution and BRAF kinase activation." (PMID 23844038, 2013). "Among the genes affected by BRAF mutation-specific methylation changes, we found enrichment of several cancer-related pathways, including the PI3 kinase and Wnt signaling pathways." (PMID 23324568, 2013). "BRAF mutations were also identified in other cancer cell lines, including gliomas, sarcomas, and lung and colon cancer." (PMID 23420786, 2013). "Mutational analysis for KRAS and BRAF discloses some possible interactions between different tumorigenic pathways of low- and high-grade carcinomas." (PMID 23388101, 2013). "A number of studies have suggested that multifocal carcinomas have independent origins due to the heterogeneous distribution of BRAF mutations in multifocal PTC." (PMID 23599804, 2013).
cancer (continued). "In pT1/T2 carcinomas, BRAF mutation was detected in 65.9% and this difference was statistically significant (p = 0.007)." (PMID 23883275, 2013). "Recent high-throughput-sequencing of the cancer genome has identified oncogenic mutations in BRaf genetic locus as one of the critical events in melanomagenesis." (PMID 22611400, 2012). "In the current study, we have examined the differential effects of IPA3, either alone or in combination with some other MAPK cascade inhibitors, on cancer lines with known mutations in Ras and BRAF genes." (PMID 22869096, 2012). "Despite tremendous efforts made to target BRAF for cancer treatment, the correlation between BRAF mutation and patient survival is still a matter of controversy." (PMID 23056577, 2012). "The oncogene BRAF is frequently mutated in other human cancers constitutively activating the MAPK pathway." (PMID 23209607, 2012). "Cancer patients with the BRAF driver mutations are postulated to be sensitive to B-Raf inhibitors such as vemurafenib, dabrafenib, and GDC-0879." (PMID 23006971, 2012). "Since then, numerous studies investigated the role of BRAF mutation in cancer development and progression." (PMID 23056577, 2012). "The efficacy GDC-0879 is related to the BRAF V600E mutational status in the cancer cells and inhibition of downstream MEK and ERK activity." (PMID 23085539, 2012). "We analyzed exon 15 of BRAF to search for a V600E substitution, the most common activating mutation of BRAF, which is observed at high frequencies in various cancers." (PMID 22994622, 2012). "Extended investigations into the histology and molecular characteristics of these BRAF mutant/MSS cancers will help to reveal further potential causes of the worse prognosis observed in this cancer subgroup." (PMID 23110075, 2012). "The most common BRAF mutation, which accounts for more than 90% of cases of cancer involving this gene, is the T1799A transversion, converting valine to glutamic acid at position 600 (V600E)." (PMID 23209607, 2012). "A significant difference in the rate of CIN between the two groups was evident at the 18q chromosomal region with the BRAF wild type/MSS cancers having significantly greater loss at the 18q chromosomal region." (PMID 23110075, 2012). "They revealed that high frequency of BRAF mutation is a common phenomenon in multiple types of cancers." (PMID 23056577, 2012). "In fact, even kinase-dead BRAF mutations, which have been observed in human cancer, the mutant B-Raf proteins can dimerize with Raf-1, when stimulated by the mutant Ras protein and activate the Raf/MEK/ERK cascade." (PMID 23085539, 2012). "The mechanism underlying the association of CIN with advanced stage in BRAF mutant/MSS cancers requires elucidation." (PMID 23110075, 2012). "The greatest loss in BRAF mutant/MSS cancers occurred at 8p (26/44, 59%), and the least at 5q (19/49, 39%)." (PMID 23110075, 2012). "The selective BRAF inhibitor, PLX4720, has been shown to inhibit MAPK phosphorylation in BRAF mutated cancer cell lines." (PMID 22792460, 2012).